ARID4B (AT-rich interaction domain 4B)
Diseases named in the same sentence as ARID4B in open-access papers (continued):
Sharing a sentence is not in itself a finding about the gene and the disease.
prostate carcinoma (continued). "In prostate cancer, especially in the PTEN-null phenotype, upregulation of ARID4B activates the PTEN-PI3K pathway through specific transactivation of both PIK3CA and PIK3R2, which favors tumor progression and correlates positively with prostate cancer recurrence." (PMID 38137006, 2023). "In addition, the human prostate cancer cell lines PC3, DU145, LNCaP, and C4-2B expressed higher levels of ARID4B protein than the normal (nonmalignant) prostate epithelial cell lines RWPE-1, PZ-HP-7, and HPrEC." (PMID 31551414, 2019).
breast tumor (2 papers, 2012 to 2016). "High expression of Arid4b enhances cell migration and invasion and, conversely, knockdown of Arid4b inhibits metastasis of breast tumor cells to the lungs." (PMID 22693453, 2012).
colorectal cancer (2 papers, 2022). A primary or metastatic malignant neoplasm that affects the colon or rectum. "Circ-SMARCA5 exerts a suppressive impact on colorectal cancer malignancy via sequestering miR-39-3p to elevate AT-rich interaction domain 4B (ARID4B)." (PMID 35365168, 2022).
leukemia (2 papers, 2023). A malignant (clonal) hematologic disorder, involving hematopoietic stem cells and characterized by the presence of primitive or atypical myeloid or lymphoid cells in the bone marrow and the blood. "Contrary, in human leukemias, ARID4B seems to exert a tumor suppressor activity, and either its downregulation or heterozygous inactivating mutations alongside mutations in ARID4A in vivo lead to leukemic transformation through indirect epigenetic mechanisms." (PMID 38137006, 2023). "Although we show here that ARID4B is essential to KMT2A-r ALL cells, the exact mechanistic role of ARID4B in this aggressive type of leukemia remains to be elucidated and further explored in the context of KMT2A-r ALL patient samples." (PMID 37686014, 2023). "These efforts and additional validation experiments revealed PSIP1, CREBBP, and kinase FLT3 representing known vulnerabilities in KMT2A-r, as well as ARID4B, MBD3, and BMPR2 as potential candidates to be considered as novel therapeutic targets in this aggressive type of leukemia." (PMID 37686014, 2023).
adenoma (1 paper, 2024). A neoplasm arising from the epithelium. "Some MP-RNAs (ARID4B, CPT1A, PHKB) had increased number of partners in adenoma samples than in the paracancer samples but decreased in cancer samples." (PMID 38773399, 2024).
atherosclerosis (1 paper, 2023). A disease characterized by the build-up of fatty material and calcium deposition in the arterial wall resulting in partial or complete occlusion of the arterial lumen. "In addition, genes predicted to be targeted by the miR-17-5p, not previously associated with atherosclerosis, include ARID4B, E2F, GATA1, MEF2D, NR1I2, PURA, and RBL2." (PMID 36859458, 2023).
hypogonadism (1 paper, 2023). A disorder characterized by decreased function of the gonads. "Mice lacking arid4a and arid4b (Arid4a(−/−) and Arid4b(+/−)) exhibit the progressive loss of male fertility with hypogonadism and spermatophore hypoplasia." (PMID 37254055, 2023).
male infertility (1 paper, 2025). The inability of the male to effect fertilization of an ovum after a specified period of unprotected intercourse. "Several studies have highlighted the importance of epigenetic regulators, including ARID4B, EZH2, CUL4, and KHDRBS3, in spermatogenesis and their association with male infertility." (PMID 40949795, 2025).
melanoma (1 paper, 2023). A malignant, usually aggressive tumor composed of atypical, neoplastic melanocytes. "Fifthly, we identified ‘4‐genes risk prediction model’ (RNF11, NUDT21, RAB31, and ARID4B) and the ‘glycolysis‐prognosis‐10‐gene set’ that each confers independent prognostic significance for melanoma." (PMID 37356089, 2023). "Univariate COX analysis revealed that RAB31, NUDT21, and ARID4B genes were tumor suppressive in clinical melanoma samples (P < 0.1)." (PMID 37356089, 2023).
metastatic disease (1 paper, 2012). "Our current studies have therefore focused on Arid4b, which maps within the chromosome 13 locus and whose mRNA expression was positively associated with metastatic disease and tumor growth, suggesting a possible causative role as a progression modifier." (PMID 22693453, 2012). "Because this association was significant among patients with ER-positive tumors who were lymph node negative at the time of diagnosis, this finding indicated that ARID4B expression level is predictive of patient progression to metastatic disease." (PMID 22693453, 2012). "The mouse gene and human ARID4B are highly conserved, and among women with ER+ tumors ARID4B expression level is predictive of which patients will progress to develop metastatic disease." (PMID 22693453, 2012).
myeloproliferative disorder (1 paper, 2020). A clonal hematopoietic stem cell disorder, characterized by proliferation in the bone marrow of one or more of the myeloid (i.e., granulocytic, erythroid, megakaryocytic, and mast cell) lineages. "Arid4b-deficient mice display a perturbed haematopoiesis in all haematopoietic blood lineages and with time develop myeloproliferative disorders and AML, indicating a role as positive regulator of myeloid differentiation." (PMID 31900031, 2020).
neuroblastoma (1 paper, 2025). Neuroblastoma (NB) is the most common solid, extracranial childhood tumor. "As most epigenetic regulators, such as ARID4B and transcription factors, are difficult to target, we tested if we could identify targetable vulnerabilities of indisulam-resistant neuroblastoma tumor cells by focusing on kinases." (PMID 40962798, 2025). "However, the information on ARID4B and PHF12 in cancer, particularly in neuroblastoma, was scarce." (PMID 40962798, 2025).
prostate adenocarcinoma (1 paper, 2019). "Results revealed that expression of ARID4B was higher in prostate adenocarcinoma compared to prostate hyperplasia (left), shown as an increase in the number of ARID4B-positive cells in prostate adenocarcinoma samples (left)." (PMID 31551414, 2019). "Furthermore, expression of ARID4B and PTEN was negatively correlated in human prostate adenocarcinoma, while expression of ARID4B and p110α was positively correlated." (PMID 31551414, 2019).
retinoblastoma (1 paper, 2014). A malignant tumor that originates in the nuclear layer of the retina. "ARID1 is perhaps analogous to ARID4A and ARID4B in animals, which associate with the histone deacetylase complex and are involved in male fertility control by acting in the Retinoblastoma (RB) pathway." (PMID 25057814, 2014).
tumor (22 papers, 2012 to 2025). "A poor prognosis for HCC patients was indicated by high ARID4B expression, which was found to be associated with tumor-node-metastasis stages, Edmondson-Steiner grades, vascular invasion, and tumor size." (PMID 35402625, 2022). "As predicted by the genetic linkage and gene expression data, higher expression of Arid4b is associated with more rapid tumor growth in animal models, as well as increased tumor cell motility and invasion." (PMID 22693453, 2012). "In vitro assays were performed to address the potential affect of the Arid4b polymorphisms on tumor cell behavior." (PMID 22693453, 2012). "This PTEN/ARID4B/PIK3CA signature robustly stratified patients into those at high versus low risk for tumor recurrence (HR = 4.58, P = 0.006 in the GSE40272 dataset; HR = 3.23, P = 0.002 in the GSE21032 dataset; HR = 1.51, P = 0.025 in the TCGA dataset; Statistical analysis: log-rank test)." (PMID 31551414, 2019). "Taken together these results demonstrate a causal role for Arid4b in tumor growth and metastatic progression and suggest that mechanisms of action involve modification of epigenetic state via the mSIN3A complex and regulation of the conserved Tpx2 gene network." (PMID 22693453, 2012). "In hepatocellular carcinoma, levels of ARID4B show a positive correlation with tumor progression and adverse prognosis." (PMID 38137006, 2023). "In mice, ARID4B expression has been found to promote the proliferation and invasiveness of malignant cells; in fact, expression increases tumor growth in vivo and in vitro." (PMID 38137006, 2023). "In the DU145 (PTEN-intact) cells, knockout of ARID4B also suppressed cell growth and tumor formation in xenografts, but less than in PC3 cells." (PMID 31551414, 2019). "Ectopic expression of Arid4b promoted primary tumor growth in vivo as well as increased migration and invasion in vitro, and the phenotype was associated with polymorphisms identified between the AKR/J and DBA/2J alleles as predicted by our genetic analyses." (PMID 22693453, 2012). "These statistical analyses of patient data suggest that ARID4B might have the strongest tumor promoting effect of the three co-amplified genes." (PMID 33921698, 2021). "In addition, ablation of ARID4B sufficiently inhibited cell proliferation and tumor formation in tumor xenograft experiments." (PMID 31551414, 2019). "Similarly, we showed that the PTEN/ARID4B/PIK3CA signature has greater predictive power for tumor recurrence than any individual gene alone or two genes combined." (PMID 31551414, 2019). "Ectopic expression of Arid4b at a physiologically relevant two- to three-fold increased level resulted in a 3-fold increase in orthotopic tumor mass relative to controls for Met-1 cells expressing the DBA allele, while the AKR allele induced 1.9-fold larger tumors versus control cells." (PMID 22693453, 2012). "In addition, ARID4B may promote cancer cell activity through additional pathways unrelated to PTEN tumor suppressor function." (PMID 31551414, 2019). "Comprehensive analysis using the TCGA datasets showed that the expressions of several members of the ARID family, including ARID4B, were elevated in HCC specimens compared to non-tumor specimens." (PMID 40558499, 2025). "A multivariate Cox proportional hazards model was used to combine expression levels of PTEN, ARID4B, and PIK3CA with time to tumor recurrence from the dataset GSE4027228 into an integrated risk score model." (PMID 31551414, 2019). "In recent years, BRCAA1 gene, as an important member of ARID family, called as ARID4B, has been found to involve in the regulation of the male fertility and stem cells, ARID4B protein can regulate Rb binding protein 1, which highly suggest that ARID4B may be a tumor suppressor." (PMID 26137913, 2015).
tumor (continued). "In addition, it was reported that ARID4B acts as an oncogene in HCC, and increased ARID4B expression is correlated with vascular invasion, tumor node metastasis, tumor burden, high Edmondson–Steiner grades, and the poor prognosis of patients." (PMID 40558499, 2025). "Finally, the genes ARID4B, GALNT3, and KPNA6 were identified as other possible candidate tumor biomarkers." (PMID 37761387, 2023). "The mRNA expression of ARID3A, ARID3B, ARID4B, JARID1B, JARID1C, JARID2 in tumor tissues was more expressive in normal tissues, ARID1B, ARID3C, ARID4A, ARID5A, ARID5B, JARID1A mRNA expression in tumor tissues were lower than that in the normal tissues (p<0.05)." (PMID 33592583, 2021).
cancer (19 papers, 2012 to 2025). A tumor composed of atypical neoplastic, often pleomorphic cells that invade other tissues. "A study to evaluate the loss of function of ARID1A and ARID4B in both normal and cancer cells is necessary to verify specific effects on the TGF-β pathway, such as adding exogenous TGF-β in a rescue study." (PMID 38137006, 2023). "Silencing experiments also showed that ARID4B is associated with developing cancer-associated characteristics." (PMID 38137006, 2023). "Here, the authors show that ARID4B is a synthetic essential gene in these cancers in which deficiency of PTEN prompts the AKT-ARID4B feedback loop required for activation of the PI3K-AKT signaling pathway." (PMID 31551414, 2019). "For this reason, this study supports the hypothesis that the ARID4B gene is associated with promoting cancer-associated characteristics." (PMID 38137006, 2023). "In addition, the RNA-Seq analysis performed in ARID4B clones revealed 410 dysregulated genes affecting different pathways, some associated with cancer and metastasis." (PMID 38137006, 2023). "Thus, the expression or function of ARID1A and ARID4B genes seem to have opposite associations in cancer development." (PMID 38137006, 2023). "Higher ARID4B expression has been identified as a risk factor for diverse cancer types." (PMID 38137006, 2023). "Our results shed light on the importance of ARID4B mutations in cancer." (PMID 38137006, 2023). "For example, ARID4B, encodes a protein with sequence similarity to retinoblastoma-binding protein-1, which functions in diverse cellular processes including proliferation, differentiation, apoptosis, oncogenesis, and cell fate in cancer cells." (PMID 36859458, 2023). "This review will explore the physiological and pathological roles of ARID4B in early embryogenesis and development, as well as cancer’s initiation, progression, and metastasis." (PMID 40558499, 2025). "We recently found an important hotspot in ARID4B position 939 involving four cancer types (uterine, stomach, colorectal, and thymus)." (PMID 38137006, 2023). "Cancer with amplified ARID4B displayed a 29% increase in ARID4B expression, which was highly significant (1.17 × 10−8)." (PMID 33921698, 2021). "Compared to amplifications of MRCKα and AKT3, amplifications of ARID4B showed the strongest enrichment in the Basal cancer subtype." (PMID 33921698, 2021). "In PC3 cells, knockout of ARID4B not only efficiently constrained cell growth, but also significantly suppressed aggressiveness of cancer cells, including cell migration, cell invasion, and tumorsphere formation." (PMID 31551414, 2019). "In contrast, ablation of ARID4B inhibits the PI3K-AKT pathway, and compromises cancer progression in prostate harboring PTEN deficiency (right)." (PMID 31551414, 2019). "This includes a loss at 1q42.2-q42.3 which contains ARID4B, a chromatin-remodeling gene that interacts with RB1, and reduced expression is associated with the development of breast and other cancers." (PMID 28945760, 2017). "Furthermore, with the help of knockdown methodologies, a reduction in metastasis has also been demonstrated, which indicates that ARID4B would also have an important role in this type of cancer." (PMID 38137006, 2023). "However, there are several studies related to the role of ARID4B and its participation in the development of different types of cancer." (PMID 38137006, 2023). "ARID4B was reported to have a tumor suppressor effect in other cancers, such as prostate cancer and leukemia, so circSMARCA5 may indirectly play a role in suppressing cancer through this pathway." (PMID 35712125, 2022). "Using databases of cancer-related hotspots, we have found that the ARID4B gene has two hotspots that have never been validated." (PMID 38137006, 2023).
neurodevelopmental disorder (1 paper, 2025). A behavioral and cognitive disorder with onset during the developmental period that involves impaired or aberrant development of intellectual, motor, or social functions. "In turn, rest-induced (down in mice) ARID4B might interact with rest-induced BCL11A (up in mice); both are associated with neurodevelopmental disorders." (PMID 40725218, 2025).
ARID4B also shares sentences with these, for which no sentence is quoted: Insulin resistance (4 papers); pancreatic cancer (3); type 2 diabetes (3); Cirrhosis (2); myeloid malignancies (2); sarcopenia (2); B cell lymphoma (1); benign tumors (1); brain cancer (1); brain tumors (1); cervical cancer (1); depression (1); ductal breast carcinoma (1); heart failure (1); hepatocellular adenoma (1); hepatocellular carcinoma (1); kidney disease (1); liver cancer (1); lung carcinoma (1); metabolic disease (1); metabolic syndrome (1); neurodegenerative disease (1); neuromuscular disease (1); Obesity (1); ovarian carcinoma (1); ovarian tumor (1); pancreatic ductal adenocarcinoma (1); prostate (1); rectal cancer (1); renal carcinoma (1).
A further 1 disease shares a sentence with ARID4B in 1 paper.